XDH (xanthine dehydrogenase)
Diseases named in the same sentence as XDH in open-access papers (continued):
Sharing a sentence is not in itself a finding about the gene and the disease.
alcoholic liver damage (2 papers, 2015 to 2019). "As discussed in Section 3.2, “Target prediction of TCM,” ZZDHT decoction has been applied to treat alcoholic liver disease by targeting CYP2E1, XDH, NOS2, and PTGS2." (PMID 30846939, 2019). "The authors found that ZZDHT may exert antioxidant effects to regulate reactive oxygen species, thereby treating alcoholic liver disease by targeting cytochrome P450 2E1 (CYP2E1), xanthine dehydrogenase (XDH), nitric oxide synthase 2 (NOS2), and prostaglandin-endoperoxide synthase 2 (PTGS2)." (PMID 30846939, 2019).
bladder urothelial carcinoma (2 papers, 2021 to 2022). "However, XDH mRNA expression was higher in bladder urothelial carcinoma (BLCA)." (PMID 34496841, 2021).
iron deficiency (2 papers, 2020 to 2025). "The proteome profile identified 4 novel factors to be conversely regulated upon iron deficiency versus iron excess, namely CPT1A, MMP14, XDH, and PYGL." (PMID 33023155, 2020).
kidney toxicity (2 papers, 2012 to 2025). "Thus, the high expression level of XDH might also be associated with arsenic-induced kidney toxicity." (PMID 40559956, 2025).
Molybdenum cofactor deficiency (2 papers, 2012 to 2017). "Molybdenum cofactor deficiency, xanthinuria type III, a rare autosomal recessive neurodegenerative disorder is characterised by a combined deficiency of molybdenum cofactor-dependent enzymes sulfite oxidase, xanthine dehydrogenase and aldehyde oxidase." (PMID 28877755, 2017).
purine metabolic disorder (2 papers, 2024 to 2025). "For XDH to participate in the purine metabolism, a purine metabolic disorder may affect the cell energy metabolism and redox state, which affects the function of the podocyte." (PMID 40949127, 2025).
renal cell carcinoma (2 papers, 2022 to 2025). "C1QBP promotes the catabolism of hypoxanthine and elevates the apoptosis of renal cell carcinoma cells by modulating xanthine dehydrogenase (XDH)-mediated oxygen species (ROS) generation." (PMID 40454173, 2025).
adrenocortical carcinoma (1 paper, 2022). "The XDH expression was a poor prognostic factor in adrenocortical carcinoma and kidney chromophobe but a good prognostic factor in liver hepatocellular carcinoma clinical outcomes." (PMID 35664305, 2022). "Using the TIMER2.0, we found that the expression of XDH was a poor prognostic factor in adrenocortical carcinoma and kidney chromophobe but a good prognostic factor in liver hepatocellular carcinoma clinical outcomes." (PMID 35664305, 2022).
glaucoma (1 paper, 2017). Increased pressure in the eyeball due to obstruction of the outflow of aqueous humor. "To establish whether expression of Mut-XDH is involved in the generation of glaucoma, we measured the levels of XDH mRNA, protein and phthalazine/hypoxanthine oxidizing activity in the eye and liver of female WT, Mut-XDHTg/Glau and Mut-XDHTg/Norm mice." (PMID 28894266, 2017). "Regardless of the presence/absence of glaucoma, a specific XDH protein band in either WT or transgenic animals could not be detected upon Western blot analysis." (PMID 28894266, 2017). "This along with the appearance of glaucoma in only one of the 6 transgenic lines generated, supported the hypothesis that the pathologic phenotype was not due to expression of the Mut-XDH transgene, but rather to its insertion into a critical region of the genome." (PMID 28894266, 2017).
HPRT-deficiency (1 paper, 2017). "First, we observed renal lesions only when the inhibition of XDH by allopurinol was associated with HPRT-deficiency and serum accumulation of xanthine." (PMID 28282408, 2017).
Hypercalcemia (1 paper, 2022). An abnormally increased calcium concentration in the blood. "Cellular hypercalcemia causes the breakdown of sarcoplasmic phospholipids and cytoskeleton protein, alters contractile protein’s efficiency and calcium affinity, and changes the tertiary structure of certain enzymes such as xanthine dehydrogenase to xanthine oxidase." (PMID 36189311, 2022).
Hypoglycemia (1 paper, 2023). A decreased concentration of glucose in the blood. "The dose of 2-DG was limited by its toxicity associated with hypoglycemia symptoms 64, while its combination with the XDH inhibitor febuxostat was well tolerated in this study." (PMID 36778128, 2023).
ischemic disease (1 paper, 2024). Lack of blood supply to an area of the body, resulting in impairment of tissue oxygenation. "To address these gaps in knowledge, we performed a linear drug-target MR analysis to investigate the effects of reducing uric acid levels by XDH inhibition on the risk of ischemic diseases in individuals whose data are in the UK Biobank." (PMID 38228698, 2024).
mesothelioma (1 paper, 2021). A usually malignant and aggressive neoplasm of the mesothelium which is often associated with exposure to asbestos. "Moreover, high XDH mRNA expression was correlated with a worse prognosis in terms of OS and DFS in mesothelioma (MESO) and in terms of DFS in LUSC." (PMID 34496841, 2021).
myelosuppression (1 paper, 2020). Myelosuppression or bone marrow suppression is a condition in which bone marrow activity is decreased, resulting in fewer red blood cells, white blood cells, and platelets. "It is known that MTX increases the bioavailability of 6-MP by inhibiting xanthine oxidase (XO or XDH), consequently enhancing the risk of developing 6-MP-induced myelosuppression." (PMID 32481505, 2020).
myocarditis (1 paper, 2025). Myocarditis is a condition that is characterized by inflammation of the heart muscle (myocardium). "Myocarditis sera induced CAMTA2, ITGB6, NFATC2, and XDH gene expression significantly (p <0.05) above healthy sera." (PMID 40181955, 2025).
neutropenia (1 paper, 2023). A decrease in the number of neutrophils found in the blood. "A recent pathway genes association study reported the role of XDH in thiopurine-related toxicities; neutropenia, hepatotoxicity, and treatment interruption." (PMID 37251339, 2023). "This is the first study in Ethiopian ALL patients showing that persons homozygous for the minor allele of XDH rs2281547 have a higher risk on grade 4 neutropenia." (PMID 37251339, 2023). "A more recent study showed that genetic variants in XDH were associated with thiopurine metabolism and thiopurine related toxicities, including neutropenia, hepatotoxicity, and treatment interruption." (PMID 37251339, 2023). "Multivariable analysis showed that patients who carry the XDH rs2281547 CC genotype had a higher hazard (AHR 2.956, 95% CI = 1.494–5.849, p = 0.002) to develop grade 4 neutropenia than those with the XDH rs2281547 TT genotype." (PMID 37251339, 2023). "Multivariable analysis revealed that patients who are homozygous (CC) for XDH rs2281547 were 2.956 times (AHR 2.956, 95% CI = 1.494–5.849, p = 0.002) more likely to develop grade 4 neutropenia than those with the TT genotype." (PMID 37251339, 2023).
rosacea (1 paper, 2025). A chronic erythematous skin disorder that affects the face. "This study integrates network pharmacology, machine learning, and computational modeling to identify six key targets and pathways underlying Hup A’s anti-rosacea effects, with a focus on its binding mechanism to XDH." (PMID 40474977, 2025). "Future studies should employ CRISPR-based gene editing in keratinocyte or macrophage models to dissect XDH-specific roles, coupled with preclinical trials in rosacea animal models (e.g., LL37-induced mice) to assess translational potential." (PMID 40474977, 2025). "Molecular dynamics analysis of the XDH-Hup A complex was performed based on the lowest binding energy observed between XDH and Hup A, coupled with the significant upregulation of XDH expression in rosacea lesions." (PMID 40474977, 2025). "ROC curve analysis further validated the diagnostic potential of these genes, with XDH exhibiting an AUC of 0.967, RXRA with 0.916, and BCL2 with 0.693, highlighting XDH and RXRA as robust biomarkers for rosacea." (PMID 40474977, 2025). "Under inflammatory conditions, elevated XDH activity amplifies reactive oxygen species (ROS) production, exacerbating oxidative stress - a key driver of rosacea pathology." (PMID 40474977, 2025). "Mechanistically, this interaction may disrupt XDH-mediated ROS production, thereby modulating immune cell infiltration and attenuating inflammatory cascades in rosacea." (PMID 40474977, 2025). "Notably, XDH expression was significantly upregulated in rosacea lesions, whereas BCL2 and RXRA were downregulated compared to healthy controls." (PMID 40474977, 2025). "Analysis of the GSE65914 dataset showed that XDH was upregulated in rosacea lesions, while BCL2 and RXRA were downregulated, with no significant expression changes of the other genes." (PMID 40474977, 2025).
cancer (94 papers, 2011 to 2026). A tumor composed of atypical neoplastic, often pleomorphic cells that invade other tissues. "Xanthine dehydrogenase, a rate-limiting enzyme involved in purine metabolism, was associated with the expression of cancer stem biomarkers, such as CD44 or CD133 in HCC." (PMID 40311679, 2025). "Increasing evidences indicate that XDH is associated with the progression of cancer, while the insight mechanism remains elusive." (PMID 36778128, 2023). "Abnormal XDH expression and activity are observed in various types of cancer and closely associated with the clinical outcome." (PMID 36778128, 2023). "Lower XDH levels in patient tumors are associated with a severe prognosis of cancer-specific survival in several types of cancers." (PMID 32899343, 2020). "In this regard, medications inhibiting XDH activity to reduce uric acid levels should be prescribed with caution for cancer patients or patients at risk for cancer in clinical settings." (PMID 28945217, 2017). "Furthermore, XO and also XDH under hypoxic conditions are a source of ROS and subsequent DNA damage, which can cause malignant tumors, reported in several studies." (PMID 31659168, 2019). "Thus, the variability of XDH expression in different types of cancers may reflect differences in the underlying molecular and genetic mechanisms for cancer development and progression." (PMID 34496841, 2021). "monosporus, functions as a unique xanthine dehydrogenase/xanthine oxidase activator in cancer cells, promoting ROS accumulation and subsequent apoptosis." (PMID 40722996, 2025). "We found that XDH inhibitors potentiated the anti-cancer activity of 2-DG, which was accompanied with abrogation of 2-DG-induced UPR." (PMID 36778128, 2023). "It has been shown that the xanthine dehydrogenase/ Xanthine oxidase (XDH/XO) can be activated in alternol-treated cancer cells, resulting in ROS accumulation and apoptosis." (PMID 37705051, 2023). "Nucleotide pools maintained by autophagy were reported to promote the survival of cancer cells in starvation 30, while XDH is a vital and rate-limiting enzyme in purine nucleoside metabolism." (PMID 36778128, 2023). "Given that nucleosides supplementation rescued the survival of cancer cells, we proposed that ribose derived from nucleoside degradation was important for XDH-mediated cell survival upon starvation." (PMID 36778128, 2023). "The results demonstrated that XDH expression was significantly correlated with tumor purity in 18 types of cancer." (PMID 34496841, 2021). "Although the prognostic potential of XDH in several types of cancer has been reported, our work expands this knowledge of XDH in other cancers." (PMID 34496841, 2021). "Decreased XDH mRNA expression was detected in human cancers originating from the liver, bladder, breast, colon, bile duct, kidney, and hematolymphoid system." (PMID 34496841, 2021). "We also found that XDH expression was significantly downregulated in certain types of cancer, while increased XDH expression was detected in some other cancers, such as HNSC, LUAD, and LUSC." (PMID 34496841, 2021). "In this study, we found that XDH mRNA levels correlated with the prognosis of several human cancers." (PMID 34496841, 2021). "In the present study, we first comprehensively analyzed the mRNA levels of XDH and their prognostic value in cancer tissues using multiple databases." (PMID 34496841, 2021). "Next, we described the relationship between the expression of XDH and infiltrating immune cells in 40 cancer types, including HCC, using the TIMER database." (PMID 34496841, 2021). "Despite these intriguing findings, how decreased activity or expression of XDH regulates tumor immunobiology in the development and progression of cancers, including HCC, remains poorly understood." (PMID 34496841, 2021). "Analysis of the TIMER database revealed that XDH expression correlated with the infiltration status of immune cells in several cancer types, including HCC." (PMID 34496841, 2021).
cancer (continued). "In summary, a decrease in the level of XDH mRNA was detected in human cancers originating from the liver, bladder, breast, colon, bile duct, kidney, and hematolymphoid system." (PMID 34496841, 2021). "To better understand the role of XDH expression in cancers, we investigated the relationship between XDH expression and the clinical characteristics of HCC patients in the Kaplan–Meier plotter database." (PMID 34496841, 2021). "Together, these findings suggest that the level of expression of XDH mRNA has a significant impact on the prognosis of specific human cancers." (PMID 34496841, 2021). "XDH, an iron-containing protein, has an enormous influence on the development and transformation of various cancers." (PMID 32528886, 2020). "To address the specific contribution of XDH and XO in cancer, we have investigated tumor growth after syngenic tumoral cells transfer in XDH ki and XO ki mice." (PMID 31659168, 2019). "To address the regulation of tumour uricogenesis, we attempted to correlate the expression levels of these genes with tumour characteristics in the three cancer types with the highest median XDH expression, i.e. PAAD, HNSCC and liver HCC." (PMID 30104401, 2018). "We systematically addressed the existence of a correlation between the expression levels of APRT, HPRT1, XDH in the 60 human cancer cell lines and their pattern of drug sensitivity." (PMID 30104401, 2018). "Recently, XDH and its byproducts are also considered to be involved in pathological processes such as metabolic syndrome 17, hemolytic diseases 18, cardiovascular disorders 19, and cancer." (PMID 36778128, 2023). "It regulates the transcriptional activity of hypoxanthine catabolic enzyme xanthine dehydrogenase (XDH) in cancer cells presumably by regulating the mRNA level of XDH transcriptional stimulators IL-6, TNF-α, and IFN-γ, and promotes the catabolism of hypoxanthine." (PMID 37658353, 2023). "However, the safety of that combination of XDH inhibitors with anti-cancer drugs inducing UPR/autophagy should be systematically studied before the clinical trial." (PMID 36778128, 2023). "Finally, XDH inhibitors potentiated the anti-cancer activity of 2-deoxy-D-glucose that induced UPR and/or autophagy in vitro and in vivo." (PMID 36778128, 2023). "It seems that low activity of XDH provides a selective privilege to cancer cells and may also contribute to neoplastic differentiation of RAMA 37-28 cells." (PMID 37239828, 2023). "A previous pan-cancer study showed that XDH is involved in proinflammatory and immune stimulation." (PMID 35909471, 2022). "Furthermore, the prognostic potential of XDH mRNA expression in 25 types of human cancers was assessed via the GEPIA website." (PMID 34496841, 2021). "To profile XDH mRNA expression in tumor tissues and adjacent normal tissues across several types of cancer, we analyzed the Oncomine database and RNA-seq data of multiple cancers in the TCGA database." (PMID 34496841, 2021). "We hypothesized that XDH could play a significant role in regulating tumor immunology and therefore influence the outcomes of cancer patients." (PMID 34496841, 2021). "XDH, a rate-limiting enzyme to catalyze the final steps of purine metabolism, was found significantly decreased and served as a useful predictor of poor prognoses in several cancer types." (PMID 34660806, 2021). "Decreased expression of XDH mRNA in certain types of human cancer." (PMID 34496841, 2021). "Altogether our results suggest that a macrophage-specific XO inhibitor that would reduce ROS levels but leave XDH activity untouched may prove useful as a cancer therapeutic tool." (PMID 31659168, 2019). "However, how decreases in XDH expression occur during cancer progression and promote TGFβ signaling in HCC require future investigation." (PMID 28945217, 2017).
cancer (continued). "In addition, XDH expression was associated with infiltrating levels of CD4+ T cells in 9 cancer types, B cells in 12 cancer types, CD8+ T cells in 16 cancer types, DCs in 22 cancer types, macrophages in 9 cancer types, and neutrophils in 19 cancer types." (PMID 34496841, 2021). "Hence, we reasoned that inhibiting XDH could potentially change the course of cancer cell progression." (PMID 31116490, 2019). "Comparing the total expression differences of the three target genes in all cells of cancer tissue and normal tissue, the results suggest that: AEN gene expression is higher in cancer tissue than normal tissue, while LGALS4 and XDH gene expression is lower in cancer tissue." (PMID 36589748, 2022). "Although the involvement of XOR in cancer has been proposed, the mechanisms that link the XDH and XO forms to tumor-related inflammatory pathways are not clear." (PMID 31659168, 2019). "Thus, decreased expression of XDH may facilitate tumor invasion in HCC and possibly in other similar cancers with low XDH expression." (PMID 34496841, 2021). "However, the role of XDH in cancer pathogenesis has not been fully explored." (PMID 28945217, 2017).